RPL3L (ribosomal protein L3 like)
Description:
Heart- and skeletal muscle-specific component of the ribosome, which regulates muscle function. Component of the large ribosomal subunit in striated muscle cells: replaces the RPL3 paralog in the ribosome in these cells. The ribosome is a large ribonucleoprotein complex responsible for the synthesis of proteins in the cell. Inhibits myotube growth and muscle function.
Synonyms: CMD2D
Tractability: PROTAC: ubiquitination databases record sites on it.
Gene: Protein-coding gene on chromosome 16 (1,943,968 to 1,957,606, reverse strand). Ensembl gene ENSG00000140986.
Subcellular location (Human Protein Atlas): Nuclear speckles
Pathways (Reactome):
Metabolism of proteins: Eukaryotic Translation Termination; Formation of a pool of free 40S subunits; GTP hydrolysis and joining of the 60S ribosomal subunit; L13a-mediated translational silencing of Ceruloplasmin expression; PELO:HBS1L and ABCE1 dissociate a ribosome on a non-stop mRNA; Peptide chain elongation; Ribosome Quality Control (RQC) complex extracts and degrades nascent peptide; SRP-dependent cotranslational protein targeting to membrane; ZNF598 and the Ribosome-associated Quality Trigger (RQT) complex dissociate a ribosome stalled on a no-go mRNA
Metabolism of RNA: Major pathway of rRNA processing in the nucleolus and cytosol; Nonsense Mediated Decay (NMD) enhanced by the Exon Junction Complex (EJC); Nonsense Mediated Decay (NMD) independent of the Exon Junction Complex (EJC)
Cellular responses to stimuli: Response of EIF2AK4 (GCN2) to amino acid deficiency
Developmental Biology: Regulation of expression of SLITs and ROBOs
Disease: Viral mRNA Translation
Metabolism: Selenocysteine synthesis
Gene Ontology:
Molecular function: RNA binding; structural constituent of ribosome
Biological process: cytoplasmic translation; negative regulation of myoblast fusion; striated muscle contraction; translation; negative regulation of myotube differentiation; regulation of striated muscle tissue development
Cellular component: cytosolic large ribosomal subunit; membrane; cytoplasm; ribosome
Genetic constraint (gnomAD): Loss-of-function variants: 44 observed, 42.81 expected, observed/expected ratio (o/e) 1.03, 90% interval 0.81 to 1.32. The synonymous counts are far from expectation, so gnomAD's model fits this gene poorly and the ratio says little. Missense variants: 631 observed, 573.88 expected, observed/expected ratio (o/e) 1.1, 90% interval 1.03 to 1.17. Synonymous variants: 292 observed, 231.89 expected, observed/expected ratio (o/e) 1.26, 90% interval 1.14 to 1.39.
Homologues: Orthologues: chimpanzee RPL3L (99% identical), guinea pig RPL3L (97% identical), rat Rpl3l (97% identical), pig RPL3L (96% identical), mouse Rpl3l (96% identical), rabbit RPL3L (95% identical), dog RPL3L (93% identical), macaque RPL3L (87% identical), tropical clawed frog rpl3l (84% identical), Drosophila melanogaster RpL3 (69% identical), Caenorhabditis elegans rpl-3 (65% identical). Paralogues in human: RPL3 (77% identical).
Diseases named in the same sentence as RPL3L in open-access papers:
RPL3L is named in the same sentence as 35 diseases in open-access papers, as found by Europe PMC text mining. Sharing a sentence is not in itself a finding about the gene and the disease. The quoted sentences say what the papers report.
atrial fibrillation (9 papers, 2018 to 2025). A disorder characterized by an electrocardiographic finding of a supraventricular arrhythmia characterized by the replacement of consistent P waves by rapid oscillations or fibrillatory waves that vary in size, shape and timing and are accompanied by an irregular ventricular response. "Another example of newly identified genes is RPL3L, which is associated with autosomal recessive childhood-onset cardiomyopathy, while heterozygous RPL3L variants elevate risk of atrial fibrillation." (PMID 40207037, 2025). "RPL3L gene mutations cause atrial fibrillation, probably because it prolongs P-wave duration and alters neoatrial conduction." (PMID 37308880, 2023). "They identify a significant association with coding variants in RPL3L, the first ribosomal gene implicated in atrial fibrillation, and MYZAP, an intercalated disc gene." (PMID 30271950, 2018). "We observe associations with one missense (OR = 1.20) and one splice-donor variant (OR = 1.50) in RPL3L, the first ribosomal gene implicated in atrial fibrillation to our knowledge." (PMID 30271950, 2018). "The missense variant rs140185678 in RPL3L is also independently associated with atrial fibrillation (MAF = 0.0363, p = 5.4 × 10−9, OR = 1.21, 95% CI: 1.14–1.30) and atrial flutter (p = 1.1 × 10−7, OR = 1.20, 95% CI: 1.12–1.28)." (PMID 29691392, 2018). "The RPL3L missense variant associating with atrial fibrillation is p.Ala75Val, and Ala75 is highly conserved in both RPL3L and RPL3 over a range of species (PROVEAN impact prediction scores <−2.520)." (PMID 30271950, 2018). "Interestingly, heterozygous variants in RPL3L have also been linked to atrial fibrillation in humans." (PMID 40207042, 2025). "Furthermore, mutations of the human RPL3L gene have been detected in individuals with atrial fibrillation or neonatal dilated cardiomyopathy." (PMID 37080962, 2023). "To assess the relationship between RPL3L and atrial fibrillation further, we tested all 15 low-frequency coding variants in the gene for association with atrial fibrillation after conditioning on p.Ala75Val and c.1167+1G>A (significance threshold = 0.05/15 = 0.0033)." (PMID 30271950, 2018). "Joint analysis of all data sets yielded genome-wide significant association with atrial fibrillation of all three variants, RPL3L Ala75Val (OR: 1.20, P = 1.7 × 10−14), RPL3L c.1167+1G>A (OR: 1.50, P = 5.0 × 10−10), and MYZAP p.Gln254Pro (OR: 1.38, P = 3.3 × 10−10)." (PMID 30271950, 2018). "Four of these genes have previously been linked in GWAS to atrial fibrillation (TTN, RPL3L, PKP2, PMVK)." (PMID 38390584, 2024). "Atrial fibrillation was associated with rare variations in 8 genes (TTN, RPL3L, KLF1, TET2, NME3, KDM5B, PKP2, PMVK)." (PMID 38390584, 2024). "Atrial fibrillation (ICD10 code I48) was associated with rare variation in 8 genes (TTN, RPL3L, KLF1, TET2, NME3, KDM5B, PKP2, PMVK)." (PMID 38390584, 2024). "In summary, we report the association of three low-frequency coding variants in RPL3L and MYZAP with increased risk of atrial fibrillation." (PMID 30271950, 2018). "The two RPL3L variants are not correlated (D’ = 1, r2 = 0.00024), and when conditioned on each other, both associations with atrial fibrillation remained." (PMID 30271950, 2018). "When testing for association with ECG traits using all ECGs irrespective of rhythm and history of atrial fibrillation, p.Ala75Val in RPL3L associates more significantly with ECG measurements and p.Gln254Pro in MYZAP associates with various P wave indices, R amplitude, and T wave indices." (PMID 30271950, 2018).
dilated cardiomyopathy (7 papers, 2020 to 2023). Cardiomyopathy which is characterized by dilation and contractile dysfunction of the left and right ventricles. "Recently, biallelic variants in ribosomal protein L3-like (RPL3L) have been reported to be associated with severe neonatal dilated cardiomyopathy (DCM) and CHF." (PMID 38254943, 2023). "RPL3L is a newer and likely pathogenic gene associated with a severe form of early-onset dilated cardiomyopathy with poor prognosis necessitating heart transplantation." (PMID 36291431, 2022). "In this report, we provide evidence that bi-allelic mutations in RPL3L cause a severe dilated cardiomyopathy during the neonatal period." (PMID 32514796, 2020). "This is the first case report of RPL3L-associated neonatal dilated cardiomyopathy in China." (PMID 37308880, 2023). "Previous studies have shown that it was specific highly expressed in human muscle and a missense mutation in the human RPL3L gene could cause neonatal dilated cardiomyopathy." (PMID 36407004, 2022). "In conclusion, we report that bi-allelic pathogenic variants in RPL3L are causative of an early-onset, severe neonatal form of dilated cardiomyopathy, and we show for the first time that cytoplasmic ribosomal proteins are involved in the pathogenesis of non-syndromic cardiomyopathies." (PMID 32514796, 2020). "The differentially expressed genes included several causative genes of congenital heart defects, hypertrophic cardiomyopathy, congenital long-QT syndrome, muscular dystrophy, and dilated cardiomyopathy (e.g., Acta2, Ankrd1, Scn4b, Ano5, Rpl3l, Cenpf)." (PMID 35942699, 2022). "RPL3L-ribosomes appear to influence translation of the overall transcriptome, but they especially affect that of transcripts of genes related to cardiac muscle contraction and dilated cardiomyopathy." (PMID 37080962, 2023).
cardiomyopathy (4 papers, 2020 to 2025). A disease of the heart muscle or myocardium proper. "In humans, missense mutations in RPL3L cause cardiomyopathy and lethal arrhythmia, and one of these studies showed no alteration in the patient’s mitochondrial genome due to the RPL3L missense mutation." (PMID 36733907, 2023). "Additionally, predicted loss-of-function (pLOF) variants in RPL3l are associated with an increased risk of atrial fibrillation and cardiomyopathy, highlighting its potential role in cardiac rhythm regulation and myocardial remodeling." (PMID 40734976, 2025). "Both Myl4 and Sdha are highly expressed in BXD mouse hearts with a mean expression of 10.8 and 14.6, respectively, are significantly correlated with Rpl3l and are functionally related to cardiomyopathy." (PMID 38254943, 2023). "Thus, to understand the role of Rpl3l in the heart tissue and cardiomyopathy, we identified genes that are significantly correlated with Rpl3l expression in the heart of BXD mice using the GeneNetwork database." (PMID 38254943, 2023).
Arrhythmia (3 papers, 2023 to 2024). Any cardiac rhythm other than the normal sinus rhythm. "This is the first report of arrhythmia and first-degree atrioventricular block caused by variants in the RPL3L gene." (PMID 37308880, 2023). "Eight of these associations were novel (LMNA, SMAD6, HSPB9, TMEM95, KLF1, TET2, NME3, KDM5B) and 5 genes have previously been linked to arrhythmias (SCN5A, TTN, RPL3L, PKP2, PMVK)." (PMID 38390584, 2024).
heart failure (3 papers, 2022 to 2025). Inability of the heart to pump blood at an adequate rate to meet tissue metabolic requirements. "As an example, we recently identified biallelic pathogenic variants in the ribosomal protein L3 like (RPL3L) gene as cause of an early-onset, rapidly progressive neonatal DCM and heart failure." (PMID 40207042, 2025). "This is the second report in the literature to the best of our knowledge and our findings support the pathogenicity of biallelic RPL3L pathologic variants associated with rapidly progressive neonatal DCM and heart failure with a poor prognosis." (PMID 35323613, 2022).
diabetes (2 papers, 2022 to 2023). "Pediatric patients with RPL3L mutations developed severe DCM in the absence of comorbidities such as atherosclerosis, hypertension, myocardial ischemia or diabetes mellitus, highlighting a direct connection of RPL3L with DCM and immune-mediated inflammation." (PMID 38254943, 2023).
atrioventricular block (1 paper, 2023). A heart block that is initiated in the atrioventricular node. "Notably, the premature atrial beats and atrioventricular block in the patient we describe have not been previously reported in patients with RPL3L pathogenic variants." (PMID 37308880, 2023).
congestive heart failure (1 paper, 2023). Failure of the heart to pump a sufficient amount of blood to meet the needs of the body tissues, resulting in tissue congestion and edema. "Recently, several novel biallelic variants in the RPL3L (ribosomal protein L3-like) gene have been reported in neonates and infants with early-onset severe DCM and congestive heart failure (CHF), typically requiring heart transplantation." (PMID 38254943, 2023).
diabetic cardiomyopathy (1 paper, 2023). Diabetic cardiomyopathy is a disorder of the heart muscle in people with diabetes. "Pathways such as “diabetic cardiomyopathy”, “focal adhesion”, “oxidative phosphorylation” and “DCM” were significantly associated with Rpl3l." (PMID 38254943, 2023). "While “diabetic cardiomyopathy” included 39 of the correlated genes (FDR p = 0.00045), 22 Rpl3l-correlated genes were involved in the “DCM” pathway (FDR p = 0.00078)." (PMID 38254943, 2023).
Duchenne muscular dystrophy (1 paper, 2023). Duchenne muscular dystrophy (DMD) is a neuromuscular disease characterized by rapidly progressive muscle weakness and wasting due to degeneration of skeletal, smooth and cardiac muscle. "Furthermore, an AAV-mediated knockdown of Rpl3l mRNA in the mdx mouse model of Duchenne muscular dystrophy and their wild type counterparts was reported to improve skeletal muscle function." (PMID 36733907, 2023).
endometrial cancer (1 paper, 2024). Primary or metastatic malignant neoplasm involving the endometrium (mucous membrane that lines the endometrial cavity). "RPL3L (Ribosomal Protein L3 Like) has also been reported as an epigenetically silenced tumor suppressor in endometrial cancer, however its function in AML is yet to be explored." (PMID 38650628, 2024).
fibrosis (1 paper, 2023). the formation of excess fibrous connective tissue in an organ or tissue in a reparative or reactive process. "Histopathologic analysis revealed no obvious changes in myofiber size as determined by wheat germ agglutinin (WGA) staining or in the extent of cardiac fibrosis as visualized by Masson’s trichrome staining in the heart of Rpl3l−/− mice compared with that of control mice." (PMID 37080962, 2023).
melanoma (1 paper, 2022). A malignant, usually aggressive tumor composed of atypical, neoplastic melanocytes. "In addition, the somatic substitution p.P172L (c.C515T) in RPL3L has previously been associated with melanoma." (PMID 36482893, 2022).
mitral valve regurgitation (1 paper, 2023). "These variants associated with severe neonatal DCM, patent foramen ovale, tricuspid and mitral valve regurgitation, first-degree atrioventricular block, occasional premature atrial contractions, and paroxysmal ST segment changes, which further extends the phenotype spectrum of RPL3L variations." (PMID 37308880, 2023).
osteogenesis imperfecta (1 paper, 2021). Osteogenesis imperfecta (OI) comprises a heterogeneous group of genetic disorders characterized by increased bone fragility, low bone mass, and susceptibility to bone fractures with variable severity. "Moreover, PPI and enrichment analysis indicated that VTN and RPL3L and their interacting proteins are significantly associated with osteoclast differentiation, which is associated with HI in osteogenesis imperfecta." (PMID 33078831, 2021).
pancreatic cancer (1 paper, 2021). "Interestingly, we observed that there are reports of mutations and copy number variation in PAIP2B, PRDX1, RNASE1, BARD1, UHMK1, and RPL3L genes associated with pancreatic cancer." (PMID 34912796, 2021).
sickle cell disease (1 paper, 2022). Sickle cell anemias are chronic hemolytic diseases that may induce three types of acute accidents: severe anemia, severe bacterial infections, and ischemic vasoocclusive accidents (VOA) caused by sickle-shaped red blood cells obstructing small blood vessels and capillaries. "Bantu, Afro-related ethnolinguistic cultural groups, and Latin America have a similar low proportion of pathogenic variants in most of the sickle cell disease-specific genes, except in MY O 7B, CPS1, COL6A3, MTRR, SLC22A5, ABCC1, and RPL3L." (PMID 35812734, 2022).
virus infection (1 paper, 2010). "Down-regulation of IL15, NOS2A, CCR4 and up-regulation of IL17, CYP7A1, SELE, IL5, RPL3L genes in both patient categories indicative of response to p-H1N1-09 virus infection." (PMID 20957032, 2010).
heart disease (1 paper, 2025). "In human patients, the toxic gain-of-function of PRL3L driven by missense mutations likely causes severe heart disease symptoms, which cannot be recapitulated by Rpl3l knockout in mice." (PMID 40869184, 2025). "This supports the idea that the RPL3L mutations have a gain of toxic function and genetic knockout of RPl3l in mice may not necessarily cause heart diseases as observed in RPL3L-null humans." (PMID 40869184, 2025). "Publicly available human genome sequencing databases reveal more than ten individuals with homozygous RPL3L knockouts, with no reported cases of heart disease." (PMID 40869184, 2025).
RPL3L also shares sentences with these, for which no sentence is quoted: cardiac hypertrophy (2 papers); catecholaminergic polymorphic ventricular tachycardia (2); asthma (1); atherosclerosis (1); atrial flutter (1); bone marrow failure (1); cancer (1); congenital long-QT syndrome (1); COVID-19 (1); Hypertension (1); hypertrophic cardiomyopathy (1); muscular dystrophy (1); myocardial ischemia (1); nicotine addiction (1); Patent foramen ovale (1); tumor (1).